INS (insulin)
Diseases named in the same sentence as INS in open-access papers (continued):
Sharing a sentence is not in itself a finding about the gene and the disease.
periodontitis (continued). "Chronic inflammation from periodontitis has been shown to induce activation of the NF-κB pathway, leading to an increase in pro-inflammatory cytokines that directly impair insulin action." (PMID 40136728, 2025). "The synergistic impact of elevated pro-inflammatory cytokines (TNF-α, IL-6, and resistin) and reduced APN disrupts insulin signaling pathways, thereby affecting periodontitis." (PMID 41246338, 2025). "Individuals who used insulin and oral hypoglycemic agents were more likely to have higher-grade periodontitis (p = 0.006 and p = 0.030, respectively)." (PMID 39157205, 2024). "The mechanisms by which IR is induced in insulin-targeting tissues (the liver, visceral adipose tissue, and skeletal muscle) are explained, clarifying the influence of periodontitis on the occurrence and development of T2D." (PMID 37321994, 2023). "Compared with the control group, the serum fasting plasma insulin level in the periodontitis group was significantly higher (P < 0.001)." (PMID 38129878, 2023). "In response to long-term stimulation with periodontitis-derived virulence factors, β-cells in a compensatory state undergo transdifferentiation or apoptosis, gradually losing the ability to secrete insulin and entering the decompensatory state." (PMID 37321994, 2023). "The effects of periodontitis microbiota on the fast plasma glucose and fast plasma insulin were also investigated." (PMID 35756043, 2022). "Periodontitis, which impairs the insulin signaling pathway and stimulates gliosis and neuroinflammation, is a risk factor for AD." (PMID 36437997, 2022). "During periodontitis, periodontal bacteria translocate into systemic circulation and reach distant tissues, resulting in increased systemic inflammation and insulin resistance." (PMID 35327570, 2022). "Of note, in experimental mouse models of periodontitis, TLR4 loss of function inhibits the deleterious effect of periodontitis on the insulin signaling pathway, evidenced by the increased ratio of pAkt/Akt and decreased levels of TNF-α." (PMID 35327570, 2022). "A decrease in IRS-1 phosphorylation involved in the insulin signaling pathway was also reported in the adipose tissue of rat models with ligature-induced periodontitis." (PMID 35327570, 2022). "On the other hand, low MD adherence and, in particular, a low consumption of wholegrain products, increases the odds of Stage III/IV periodontitis by almost 8 times plausibly by decreasing insulin sensitivity and increasing low‐grade systemic inflammation." (PMID 35119695, 2022). "All the analyses utilizing five SNPs or four SNPs in Europeans and seven SNPs in East Asians, respectively, genetically predicted that liability to periodontitis was unrelated to HbA1C, fasting glucose, and fasting insulin using IVW or WM." (PMID 34899852, 2021). "Lastly, both fluoride application and insulin administration interventions resulted in reduction of dental caries, marginal gingivitis and periodontitis." (PMID 34563194, 2021). "Patients with severe periodontal disease had higher levels of TNF-α in the blood circulation, and the cytokines TNF-α, IL-6 and IL-1β are insulin antagonists, which play an important role in the pathogenesis of periodontitis." (PMID 32634783, 2020). "Consistently, our data further emphasized the inhibition of the insulin signaling pathway in periodontitis." (PMID 32411181, 2020). "Several studies have demonstrated lower prevalence of periodontitis, lower levels of inflammatory markers, and higher insulin sensitivity in normal-weight individuals, especially those engaged in physical activities." (PMID 29138754, 2017). "An increased level of insulin observed in the WT animals with periodontitis is consistent with results from our previous studies." (PMID 26317345, 2015). "At 18 weeks, insulin levels were significantly increased in GFPWT:WT chimeras with periodontitis relative to control animals and GFPWT:KO animals treated with LPS (p< 0.05)." (PMID 26317345, 2015).
periodontitis (continued). "We showed that periodontitis impairs hepatic insulin signaling via TLR4 and that this impairment was less in mice with whole body TLR4 loss of function (LOF) when mice were fed a HF diet." (PMID 26317345, 2015). "In our previous study, we investigated the effect of periodontitis on insulin signaling in the liver." (PMID 26317345, 2015). "Physical activity may benefit periodontitis directly by reducing inflammation and indirectly through modulatory effects on insulin sensitivity, obesity, bone density, and stress regulation." (PMID 41536749, 2026). "Periodontitis may contribute to HADHA suppression through insulin resistance-induced glucagon elevation or oral-gut-liver axis infection, activating lysosomal degradation pathways and impairing fatty acid oxidation." (PMID 40951429, 2025). "On the other hand, in periodontitis conditions, proinflammatory cytokines generated locally in periodontal tissues have the potential to permeate the bloodstream, affect distant tissues and organs, and lead to insulin resistance and beta cell destruction." (PMID 38614881, 2024). "Indeed, T1DM patients post simultaneous pancreas and kidney transplantation displayed lower GCF levels of inflammatory markers and reduced intensity of periodontitis compared to insulin-treated kidney recipients." (PMID 39000406, 2024). "Furthermore, insulin-resistant people with a healthy waist circumference showed significantly higher odds of severe periodontitis (OR = 1.47 [95% CI, 1.16–1.87]) than did insulin-sensitive people with a healthy waist circumference." (PMID 37375691, 2023). "The study also determined a positive correlation between levels of periodontal pathogens, body weight and fasting insulin, providing further grounds for a mechanism of a shared inflammatory pathway between physical activity, periodontitis and metabolic disorders." (PMID 38024148, 2023). "There is no doubt that insulin plays a crucial role in T2DM-associated periodontitis, and blood glucose instability is often accompanied by insufficient amounts of insulin." (PMID 38098816, 2023). "Microbial butyric acid had been used as the marker of periodontitis, and butyric acid could affect the body’s sensitivity to insulin." (PMID 36131931, 2022). "Increased inflammatory markers, such as cytokines and oxidative stress markers, due to periodontitis may lead to reduced or inactive insulin sensitivity, which is considered a significant event in the development of MetS." (PMID 36672511, 2022). "Interestingly, a negative correlation between the nerve growth factor (NGF) pathway and insulin signaling pathway was identified in periodontitis, which suggested a relationship between systemic diseases and periodontitis." (PMID 32411181, 2020). "We have also shown that periodontitis induced by placement of LPS soaked ligatures around molar teeth impairs hepatic insulin signaling via TLR4 and this impairment is reduced in mice with whole body TLR4 loss of function (LOF) in animals fed a high fat (HF) diet." (PMID 26317345, 2015). "This may be a reflection of the increased energetic stress induced by the infection during the development of periodontitis or a translation of insulin resistance markers to saliva." (PMID 25133529, 2014). "However, we found that the plasma glucose, the fast insulin, and alveolar bone loss were not affected by periodontitis microbiota." (PMID 35756043, 2022). "Since periodontal treatment seems to be equally able to lower hemoglobin A1c compared with other glucose lowering therapies, it may represent an alternative or adjunctive therapy to improve insulin sensitivity and glycemic control in diabetic patients with periodontitis." (PMID 32486269, 2020). "Thus, we propose that insulin signaling may be improved in mice with TLR LOF because periodontitis is less severe in these animals." (PMID 26317345, 2015).
periodontitis (continued). "In a highly inflammatory condition of periodontitis elevated TNF-α a pro-inflammatory cytokine, binds to IRS and impairs insulin signaling by serine phosphorylation of IRS-1 and reduces GLUT-4 expression." (PMID 40136728, 2025). "Inhibiting ASMase with imipramine-reduced insulin resistance and hepatic inflammation and improved both NASH and periodontitis." (PMID 37176029, 2023). "The presence of periodontitis adds to the exiting AGEs and increased AGE levels in turn impair glycemic control and increase insulin resistance." (PMID 35625570, 2022). "Indeed, during periodontitis, inflammatory lesions of the periodontal tissue may allow periodontal bacteria to disseminate into the bloodstream and reach tissues, including adipose tissue and skeletal muscles that store glucose in response to insulin." (PMID 35327570, 2022). "Based on the fact that TSE increases the risk of periodontitis and that the combined harmful effects of them can exacerbate impaired insulin signaling and insulin resistance, this study evaluated the effect of the interplay of TSE and periodontitis on glycemic control." (PMID 40260278, 2025). "Others expanded this investigation by evaluating the subgingival microflora in both insulin-dependent and non-insulin-dependent diabetic patients with periodontitis." (PMID 39000406, 2024). "Insulin sensitivity in T2DM mice with experimental periodontitis was slightly reduced but not statistically significant." (PMID 39211822, 2024). "In a recent study, it was suggested that insulin not only controlled blood glucose concentration, but it also suppressed inflammatory cytokines and ameliorated periodontitis without local periodontitis treatment in diabetic rats." (PMID 39916927, 2023). "The Gram-negative bacterial infections of periodontitis reduce the insulin-mediated glucose uptake by skeletal muscle and reduces the insulin resistance of the body." (PMID 36981453, 2023). "Interestingly, we also observed increased fasting serum insulin levels in rats, and HOMA-IR was significantly higher in the periodontitis group than in the control group but was inversely correlated with serum adiponectin levels." (PMID 38129878, 2023). "An interesting experimental study of periodontitis in C57BL/6 female mice induced by various oral pathogens (P. gingivalis, F. nucleatum, P. intermedia) depicted that pathogen-induced periodontitis elevated insulin resistance in high-fat diet-fed mice." (PMID 36467726, 2022). "In practical terms, in a rat model of type 1 diabetes mellitus with experimental periodontitis, insulin treatment significantly improved periodontitis without local periodontitis treatment." (PMID 36294882, 2022). "Hypoglycemic agents, calcium channel blockers, insulin and diuretics were significantly higher in the periodontitis patients, while a higher intake frequency of angiotensin-converting enzyme (ACE) inhibitors and antidepressants was also found in the periodontitis group." (PMID 37888091, 2023). "Thus, it was not clear from these results if impaired insulin signaling was due to less severe periodontitis or due to an inability of TLR4 (LOF) animals to respond to periodontitis/LPS, particularly in the liver." (PMID 26317345, 2015). "Simultaneously, insulin and C-peptide levels were significantly higher in the AIP cases with periodontitis versus the AIP cases without." (PMID 36013449, 2022). "P-Insulin and P-C-peptide were significantly higher in the AIP cases with periodontitis versus those without." (PMID 36013449, 2022). "T2DM patients with assumed periodontitis (vs. non-affected T2DM patients) were treated with significantly more types of medication and more often with insulin, even though the difference is numerically small." (PMID 34984561, 2022). "Insulin (p = 0.007) and C-peptide (p = 0.006) were higher in the AIP cases with periodontitis versus those without." (PMID 36013449, 2022).
periodontitis (continued). "Insulin and C-peptide were higher in AIP cases with periodontitis versus those without." (PMID 36013449, 2022).
anemia (94 papers, 2009 to 2026). A reduction in the number of red blood cells, the amount of hemoglobin, and/or the volume of packed red blood cells. "In a multivariable Cox proportional hazards model incorporating age, BMI, NT-proBNP, eGFR and LVEF, ischemic etiology, HT, anemia, insulin use, LGE presence and GLS were separately associated with adverse outcomes." (PMID 39039567, 2024). "In this article, we describe a female patient diagnosed with severe zinc deficiency who had a urinary tract infection, anemia, and insulin dysfunction." (PMID 39221327, 2024). "Proposed mechanisms for the disruption in glucose homeostasis include impaired insulin synthesis and oxidative capacity in iron-deficient tissues, induction of hepatic glucose production, and the effects of anemia-related stress responses." (PMID 38149144, 2023). "Despite the lack of significant association between glucose indices and the prevalence of anemia, using insulin had a significant association in the present study." (PMID 36894956, 2023). "The effect of high urea on insulin resistance is mediated by a decrease in erythropoietin production by uremic toxins causing anemia." (PMID 36994079, 2023). "Nevertheless, our findings that the association between rs35767 and anemia remained significant when fasting insulin levels were added to the model argue against this possibility." (PMID 28415730, 2017). "The underlying causes of these insulin abnormalities may encompass factors such as uremic toxins stemming from protein catabolism, vitamin D deficiency, metabolic acidosis, anemia, inadequate physical fitness, and cachexia." (PMID 38276262, 2023). "Furthermore, using insulin separately or in combination with oral GLDs associated positively with the prevalence of anemia with ORs of 2.60 [CI, 1.42–5.42] and (OR, 1.87 [CI, 1.30–4.37])), respectively." (PMID 36894956, 2023). "Ferritin is a marker of iron deficiency anemia but may also be a marker of oxidative stress, insulin resistance, and inflammation." (PMID 28562685, 2017). "Therefore, we speculate that acute iron loading, concomitant with partial correction of anemia following a single dose of packed erythrocytes, resulted in a trend towards reduction in insulin sensitivity and thus caused a rise in insulin secretion." (PMID 28739553, 2018). "The mean proteinuria per day was 4.28 g; most patients had anemia, with a hemoglobin level of 10.59 g/dL; the vast majority used insulin (85%); and only 19% used SGLT2 inhibitors." (PMID 40352967, 2025). "The dyspnea and chest pain, likely due to rapidly developing anemia, resolved after some improvement in the anemia, but insulin needs remained constant." (PMID 40362174, 2025). "TRT can enhance muscle mass and strength, address anemia by stimulating erythropoiesis, improve bone density, and possibly offer cardiovascular benefits by improving body composition and insulin sensitivity." (PMID 39253627, 2024). "This study reports the case of a young patient who presented to the hospital with a urinary tract infection, impaired insulin function, and anemia." (PMID 39221327, 2024). "This study examined the case of an 18-year-old woman who presented with urinary tract infection, anemia, and insulin dysfunction and was ultimately diagnosed with zinc deficiency." (PMID 39221327, 2024). "Other tests included tests of proteins, metabolites, enzymes, and markers related to insulin and anemia." (PMID 39594779, 2024). "Hormones and related therapeutic agents such as insulin, erythropoietin, and folic acid are crucial for metabolic regulation and anemia, respectively." (PMID 39252278, 2024). "Currently, the oldest sister is 36 years and shows insulin-requiring diabetes; is deaf and blind; she has solved macrocytic anaemia and with normal heart rate and echocardiography." (PMID 38037112, 2023).
anemia (continued). "We have previously reported that this modified diet study resulted in healthier, lower total cholesterol and insulin, as well as alleviated anemia, which was attributed to increased C15:0 concentrations." (PMID 35999445, 2022). "Anemia, myosteatosis, higher postoperative CBGs before TNA infusion, and insulin in the TNA are independent risk factors for postoperative severe HG." (PMID 35237639, 2022). "Univariate regression analysis showed that age, PNI, anemia, myosteatosis, type of reconstruction, pre-SPN CBGmax, POD1 CBG1, insulin and glucose in the TNA were closely associated with severe HG during SPN." (PMID 35237639, 2022). "During surgery, other noxious stimuli such as inflammation, anemia, decreased perfusion, and decreased insulin sensitivity further increase brain vulnerability." (PMID 35837483, 2022). "Multivariate logistic regression analysis of the variables (forward conditional) showed that anemia, myosteatosis, pre-SPN CBGmax, POD1 CBG1, and insulin in TNA were independent risk factors affecting HG." (PMID 35237639, 2022). "Thirdly, a larger sample size is required for the subgroup analysis to distinguish the effects of anemia from iron overload on insulin sensitivity and b-cell function." (PMID 28739553, 2018). "We demonstrated that following blood transfusion in thalassemic patients, acute iron loading accompanied by partial correction of anemia, resulted in a rise in insulin secretion and a trend towards increasing insulin resistance." (PMID 28739553, 2018). "Patients with anemia were less likely to receive antiplatelet agents, ACEIs/ARBs and statins, but more often received diuretics and insulin at hospital discharge." (PMID 29523073, 2018). "In one of them (19.1) the genetic diagnosis led to starting thiamine treatment when she had isolated neonatal diabetes and the individual is currently off insulin, yet to develop anaemia and has started using hearing aids following a hearing test." (PMID 29450569, 2018). "Vitamin D plays a role in preventing anemia but also decreases oxidative stress, insulin resistance, and inflammation." (PMID 28562685, 2017). "Examples include antidiabetes medications (eg, insulin and sulfonylurea), antihypertensives (eg, calcium channel blockers and diuretics) and anaemia medications." (PMID 27903560, 2016). "During the follow-up period, anemia improved, erythropoietin was thus discontinued and insulin requirement decreased to 105 IU." (PMID 26926587, 2016). "Examples of which include; increased insulin-induced glucose utilization following correction of anemia by erythropoietin, and improved insulin sensitivity following intravenous administration of calcitriol." (PMID 26239457, 2015). "In our study, duration of DM and use of medications like insulin, angiotensin converting enzyme inhibitor and angiotensin receptor blockers were more prevalent in patients with anemia." (PMID 25695026, 2014). "In comparison to other patients, those with anemia frequently used insulin (P < 0.0001), angiotensin converting enzyme inhibitors (P = 0.028), and angiotensin receptor blockers (P = 0.029)." (PMID 25695026, 2014). "High dose thiamine therapy in TRMA patients can improve the disease symptoms, correcting the anemia and reducing or cessating the need for exogenous insulin." (PMID 23454484, 2013). "Despite the positive effects of rosiglizatone, such as lowering fasting plasma glucose (FPG) and postprandial serum glucose, lowering HbA1c, and lowering insulin and C-peptide levels, this drug has clinically significant side effects such as edema, anemia, and weight gain." (PMID 39062500, 2024). "Anemia, decreased insulin sensitivity, and reproductive disorders are also reported." (PMID 37568636, 2023). "However, here we demonstrate that uremia decreases insulin sensitivity dose dependently in isolated myotubes suggestive of a local effect in the skeletal muscle independently of anemia." (PMID 36994079, 2023).